CCL5 (C-C motif chemokine ligand 5)
Diseases named in the same sentence as CCL5 in open-access papers (continued):
Sharing a sentence is not in itself a finding about the gene and the disease.
Autoimmunity (12 papers, 2015 to 2025). The occurrence of an immune reaction against the organism's own cells or tissues. "These shared inflammatory pathways highlight the overlapping mechanisms in vitiligo and connective tissue diseases, suggesting that the dysregulation of CXCL12 and CCL5 may serve as a common link, driving autoimmunity and sustained immune activation in these conditions." (PMID 39860439, 2025). "Elevated CCL5/RANTES levels in BMDJ/FDOJ lesions can promote immune dysregulation, enhance osteoclastic activity and sustain chronic low-grade inflammation, potentially linking BMDJ/FDOJ to systemic inflammatory and autoimmune conditions." (PMID 40426971, 2025). "We demonstrate that CD8+ T effector memory cells might drive and sustain autoimmunity via macrophage migration inhibitory factor (MIF)‐CD74 signaling to immature B cells and CC‐chemokine ligand 5 (CCL5)‐mediated recruitment of cytotoxic CD4+ T cells." (PMID 34254741, 2021). "CD26/DPP4 is a membrane-associated exopeptidase that by engaging inhibitory ligands may limit autoimmunity in mice by regulating Th1 responses, and by hydrolyzing substrates CXCL12 and CCL5." (PMID 31829262, 2019). "A role for CCL3, CCL4, CCL5 and their receptor CCR5 in Treg mediated suppression has been previously reported in autoimmunity and cancer and we demonstrate through blockade experiments both these pathways to be of fundamental importance in cells from IGRA-ve controls." (PMID 30231065, 2018). "Additionally, an absence of the LAT transporter increases CCL5 expression, an inflammatory chemokine, potentially contributing to autoimmunity." (PMID 41189639, 2025).
Cognitive impairment (12 papers, 2014 to 2025). Abnormal cognition is characterized by deficits in thinking, reasoning, or remembering. "In this paper, we review the roles and regulatory mechanisms of pro-inflammatory chemokines (CCL2, CCL3, CCL4, CCL5, CCL11, CCL20, and CXCL8) in cognitive impairment." (PMID 39011039, 2024).
dementia (12 papers, 2006 to 2025). Loss of intellectual abilities interfering with an individual's social and occupational functions. "Higher CCL5 amounts are also present in the CSF of HIV-infected patients who developed HIV-associated dementia and patients diagnosed with bacterial meningitis." (PMID 37765263, 2023). "Vpr and Nef both induce RANTES/CCL5 chemokine in microglia, causing activation of brain mononuclear cells, which correlates with clinical dementia." (PMID 21489275, 2011). "The results show that CSF chemokine concentration of MCP-1/CCL2, MIP-1α/CCL3, MIP-1β/CCL4, RANTES/CCL5, IL-8/CXCL8 and fractalkine/CX3CL1 is positively correlated with the severity of dementia and the viral load, indicating HIV induced brain damage." (PMID 16712719, 2006). "CSF samples with undetectable CCL3, CCL4 or CCL5 levels were almost entirely from nondemented patients, and detectable CSF CCL3 and CCL4 were both associated with dementia." (PMID 35865985, 2022).
epilepsy (12 papers, 2020 to 2025). A brain disorder characterized by episodes of abnormally increased neuronal discharge resulting in transient episodes of sensory or motor neurological dysfunction, or psychic dysfunction. "To this end, we analyzed the transcript levels of the inflammasome mediators Il1β, Il6, Il12, Il10, Tnfα, Cd68, Ccl2, and Ccl5, which are upregulated in pilocarpine‐ and kainic acid‐induced epilepsy models." (PMID 40608247, 2025). "Cytokine assays showed that cenobamate behaved similarly to cannabidiol by reducing the levels of Ccl5 and Cxcl10, both of which have been known to be mediators of inflammation in epilepsy." (PMID 40848130, 2025). "A positive effect has also been observed in a mouse model of epilepsy, where antagonizing the CCL5 activity resulted in lower astrocyte and microglia activation and reduced seizure severity." (PMID 37765263, 2023). "In support of the importance of CCL5 and its receptors for BBB regulation, animal studies of epilepsy demonstrated that antagonist-based inhibition of CCR5 on blood cells or blocking CCL5 can reduce BBB permeability and mitigate disease severity." (PMID 37090922, 2023). "A number of studies have found increased expression or upregulation of CCL5 in human epilepsy patients, recapitulated in rodent models of pilocarpine and KA induced epilepsy." (PMID 39086689, 2023). "We observed the upregulation of IL1β and CXCL12 in the early phase of KA-induced epilepsy and elevated levels of CCL5 at a later time point, compared with control animals." (PMID 35326336, 2022). "Although a few reports have shown that CCL5 is highly expressed in the hippocampus and piriform cortex of epilepsy and seizure patients, its regulatory role and mechanism in epileptogenesis are still unknown." (PMID 36440924, 2023). "The expression of CCL5 has been reported in several forms of epilepsy, and the levels of CCL5 in blood or cerebrospinal fluid (CSF) could be used as biomarkers of the progression of the disease." (PMID 32521797, 2020). "Here, we assessed the expression levels of CCL5, CXCL2 and CXCL12 in a KA-induced model of epilepsy." (PMID 35326336, 2022). "Furthermore, the biological role of CCL5 in recurrent epilepsy was not further explored, and further investigations are warranted." (PMID 36440924, 2023).
myocarditis (12 papers, 2009 to 2024). Myocarditis is a condition that is characterized by inflammation of the heart muscle (myocardium). "The data suggest that the Ccl5‐neutrophil subpopulation may be a potential interventional target for preventing ICIs‐associated myocarditis." (PMID 38978328, 2024). "There is a notable rise in clonal cytotoxic Temra CD8+ cells, which exhibit distinct transcriptional alterations such as the upregulation of chemokines like CCL5, in both patients with ICIs-induced myocarditis and Pdcd1-/- mice with myocarditis." (PMID 38482205, 2024). "A putative role for CC-chemokines in CCC physiopathology was raised by the demonstration that the concentrations of CCL3 and CCL5 in the cardiac tissue paralleled the intensity of myocarditis in acute and chronically Colombian-infected C3H/He mice." (PMID 32194558, 2020). "Also, CXCL10 and CCL5 were found to be among the dominant cytokines expressed in situ during acute experimental infection and chronic phase of T. cruzi-elicited myocarditis contributing to intense recruitment of activated T cells." (PMID 32393333, 2020). "To shed light on the contribution of CCL5 and its receptors CCR1 and CCR5 in Chagas heart disease, we used a model of CCC that presents fibrosis, CD8-enriched myocarditis, myocardial injury and electrical and functional abnormalities." (PMID 29696014, 2018). "Clonal cytotoxic Temra CD8+ cells are increased in the blood of patients with ICI myocarditis, as well as in the blood/hearts of Pdcd1-/- mice with myocarditis, and these CD8+ cells are featured in some unique transcriptional changes, including the upregulation of several chemokines such as CCL5." (PMID 36354777, 2022). "The intensity of acute and chronic T. cruzi-elicited myocarditis is related to the concentrations of the CC-chemokines CCL3/MIP-1α and CCL5/RANTES, but not to the concentrations of IFNγ and TNF in the cardiac tissue." (PMID 22532799, 2012).
pulmonary hypertension (12 papers, 2015 to 2026). Increased pressure within the pulmonary circulation due to lung or heart disorder. "Furthermore, a study showed that CCL5 deficiency could reverse hypoxia-induced pulmonary hypertension by restoring bone morphogenetic protein receptor 2 (BMPR2) signaling." (PMID 39119185, 2024). "A recent study showed that CCL5 expression levels were significantly elevated in the pulmonary endarterectomy tissue of patients with chronic thromboembolic pulmonary hypertension compared to healthy controls, and CCL5 may lead to pulmonary hypertension by promoting fibroblast migration." (PMID 39119185, 2024). "The differentially expressed cytokines, such as interleukin (IL)-1β, IL-8, IL-6 and chemokines like CCL5, RANTES, CXC3L1, fractalkine, monocyte chemoattractant protein (MCP)-1, and tumor necrosis factor (TNF-α) in pulmonary hypertension lesions affecting the heart, pulmonary artery and lung." (PMID 27275925, 2016).
sarcoidosis (12 papers, 2011 to 2025). Sarcoidosis is a multisystemic disorder of unknown cause characterized by the formation of immune granulomas in involved organs. "The levels of RANTES (CCl5) were significantly decreased in sarcoidosis patients compared to HP (p = 0.0003), amiodarone lung (p = 0.001), and EGPA (p = 0.005) patients." (PMID 40725075, 2025). "Specifically, when compared with healthy control T cells, there was a modest upregulation of NKG7 and CCL5 in sarcoidosis lesional T cells." (PMID 39989459, 2025). "Significantly higher protein levels or mRNA expression of chemokine C-C motif chemokine ligand 5 (CCL5) were found in the BALF of sarcoidosis patients compared with controls." (PMID 34440736, 2021). "The BALF protein levels of CCL5 were significantly higher in sarcoidosis patients as compared to controls." (PMID 21463523, 2011). "In progressing sarcoidosis, T-bet related to CCL5, IL2RB, IL15RA, and IFNG." (PMID 26696750, 2015). "In progressing sarcoidosis, T-bet correlated with CCL5, CXCR4, and CXCR7." (PMID 26696750, 2015). "In all cases CCL5 was being expressed from epithelioid histocytes, multinucleated giant cells, surrounding alveolar macrophages and other infiltrating mononuclear cells creating the sarcoid lung granulomas." (PMID 21463523, 2011). "While sarcoidosis fibroblasts also upregulated CXCL9 and CD74, they exhibited only modest increases in CCL5 and FN1." (PMID 39989459, 2025). "By contrast, T cells from sarcoidosis patients exhibited clonal expansion of terminally differentiated CD8+ effectors that expressed high levels of effector genes, including CCL5, GZMB, PRF1, IFNG, KLRG1 and ZEB2." (PMID 40469525, 2025). "Sarcoidosis fibroblasts also produced increased levels of chemoattractants (CCL2, CCL4, CCL5, CXCL9), suggesting a role in both maintaining T cell activation as well as in recruiting monocytes and T cells to the tissue microenvironment." (PMID 35668129, 2022). "This analysis further supported the crucial relationships between T-bet, CCL5, IFNG, IL2RB, and IL15RA, together with let-7d and miR-202 in progressing sarcoidosis." (PMID 26696750, 2015). "SPP1hi macrophages coexpressing CCL4 and CCL5 are not a dominant feature in systemic sclerosis or sarcoidosis." (PMID 39989459, 2025). "We assessed whether the immuno-inflammatory signal observed in BAL cells of patients with sarcoidosis was also present in their BAL fluid by measuring protein levels of two differentially upregulated genes: IL6 and CCL5." (PMID 27460362, 2016). "When comparing to control subjects, the expression levels of CC chemokines CCL3 (P = 0.043), CCL4 (P = 0.034), CCL5 (P < 0.001), and CCL8 (P = 0.031) and CXC chemokines CXCL9 (P < 0.001), CXCL10 (P = 0.002), and CXCL11 (P = 0.008) were found to be elevated in sarcoidosis patients." (PMID 26696750, 2015). "However, unlike NL and NXG, COL4A4, COL6A6, and COL11A1 were not significantly upregulated in sarcoidosis fibroblasts, and CCL5 was only modestly upregulated." (PMID 39989459, 2025). "NKG7- and CCL5-expressing T cells are not a dominant feature in systemic sclerosis or sarcoidosis." (PMID 39989459, 2025). "However, other chemokine axes (for example, CCL5/receptors and interferon inducible ELR-CXC chemokines) may also have to be dysfunctional for these sarcoidosis patients to have significantly less severe disease." (PMID 21463523, 2011). "Thus, the BALF protein level of CCL5 in those patients with stage 0 sarcoidosis would expectantly have no alterations as there are no granulomatous lesions present to produce CCL5." (PMID 21463523, 2011). "However, the dissociation of CXCL9 and CCL5 expression in sarcoidosis fibroblasts is not surprising because different external cytokine stimuli are required to induce CXCL9 and CCL5 expression in fibroblasts." (PMID 39989459, 2025).
SARS-CoV infection (12 papers, 2007 to 2025). "In contrast, CCL5, another activated T cell chemoattractant was significantly higher in aged compared to juvenile animals throughout the SARS-CoV infection period (unpaired student T-test)." (PMID 24642138, 2014). "SARS-CoV infection of myeloid dendritic cells, even unproductive, leads to chemokines upregulation of CXCL10 (IP-10), CCL2 (MCP-1), CCL3 (MIP-1a) and CCL5 (RANTES)." (PMID 32962761, 2020). "Immune cell—recruiting chemokines and cytokines, such as IP-10/CXCL-10, MCP-1/CCL-2, MIP-1α/CCL-3, RANTES/CCL-5, can be strongly induced by MERS-CoV, showing higher inducibility in human monocyte—derived macrophages by MERS-CoV as compared to than SARS-CoV infection." (PMID 32522207, 2020). "Another downregulated gene in the SARS-CoV infection is nitric oxide synthase traffic inducer (NOSTRIN) so this downregulation can induce the secretion of some proinflammatory chemokines and cytokines including CCL2, CCL5, and IL-6." (PMID 32754004, 2020). "Lung autopsies of SARS patients and in vitro SARS-CoV infections of macrophages and alveolar and bronchial cells have clearly demonstrated upregulation of numerous monocyte/macrophage, neutrophil and T cell-specific chemokines, including CCL2, CCL5, CXCL8, CXCL9 and CXCL10." (PMID 33613280, 2020).
allergic asthma (11 papers, 2014 to 2025). A asthma with a basis in a pathological type I hypersensitivity reaction. "It has been reported in some literatures that these differentially expressed proteins are related to the occurrence of allergic asthma, such as tryptase ε, MCP-1, CCL5, etc. can be released by MC." (PMID 34630102, 2021). "Among them, MCP-1, G-CSF, CD30, CCL5, E-selectin, P-selectin, OPN have been repeatedly reported as biomarkers of allergic asthma, which were highly expressed in the serum of patients." (PMID 34630102, 2021).
Granuloma (11 papers, 2011 to 2022). A compact, organized collection of mature mononuclear phagocytes, which may be but is not necessarily accompanied by accessory features such as necrosis. "Macrophage attraction to tumoral sites is induced by the secretion of chemokines in the milieu, such as chemokine (C-C motif) ligand 5 (CCL5), which also has a role in granuloma formation." (PMID 33194476, 2020). "However, the levels of CXCL10 and CCL5, readout cytokines of the MyD88-independent TLR4 pathway increased at week 5 when Sj eggs induce granuloma and then at week 6 when Sj eggs induce acute liver damage." (PMID 29321784, 2017). "Overall this study suggests that CCL2 and CCL5 may be interacting with mononuclear cells expressing specific CC chemokines receptors (CCL2 → CCR2, CCL5 → CCR1, CCR3, and CCR5) and are important biologically in the formation of pulmonary sarcoidosis granulomas." (PMID 21463523, 2011). "We found that the main cellular sources of CCL5 were epithelioid histiocytes, multinucleated giant cells, surrounding alveolar macrophages and a minor component was other inflammatory mononuclear cells that formed the non-necrotizing granulomas." (PMID 21463523, 2011).
lymphoma (11 papers, 2012 to 2025). A malignant (clonal) proliferation of B- lymphocytes or T- lymphocytes which involves the lymph nodes, bone marrow and/or extranodal sites. "We also observed increased expression of CCL5, associated with tumor recurrence, and an increase of CCR7, which controls migration of lymphoma cells into niches." (PMID 36153593, 2022). "Extensive studies on CCL5 and its receptor C-C motif chemokine receptor 5 (CCR5) indicated that CCL5 may play an important role in tumor progression in hematological malignancies, lymphomas, and a great number of solid tumors." (PMID 30200999, 2018). "The expression of CCL5, CCL18, and CCL19 was further upregulated in WDL with prominent lymphoma cell infiltration compared with that with scant lymphoma cell infiltration." (PMID 39894788, 2025). "Upregulated expression of CCR4 for CCL5, CCR6 for CCL18, and CCR7 for CCL19 was observed in lymph nodes, where lymphocytes were replaced by lymphoma cells." (PMID 39894788, 2025). "The expression of chemokine receptors, CCR4 for CCL5, CCR6 for CCL18, and CCR7 for CCL19, was upregulated in lymph nodes with conspicuous lymphoma infiltration, likely representing their expression in lymphoma cells." (PMID 39894788, 2025). "RNA sequencing revealed upregulated expression of chemokine genes, including CCL5, CCL18, and CCL19, in WDL and that of the corresponding chemokine receptor genes CCR4, CCR6, and CCR7 in the lymphoma cells." (PMID 39894788, 2025). "RNA-seq analysis also revealed that several different T-cell chemokines (including CCL5, CCL20, and CCL22) are over-expressed in the Δ3C virus-infected, versus WT virus-infected, lymphomas, a finding confirmed by qPCR analysis of tumor cell-derived cDNA." (PMID 30125329, 2018). "In EBV-positive HL, the lymphoma microenvironment is T-reg cell rich and the transformed cells secrete immunosuppressive cytokines and chemokines like IL10, CCL5, CCL20, and CXCL10." (PMID 22979947, 2012).
renal fibrosis (11 papers, 2020 to 2024). A final common manifestation of a wide variety of chronic kidney diseases characterized by glomerulosclerosis and tubulointerstitial fibrosis. "CCL5 has been implicated in the pathogenesis of perivascular inflammation, vascular dysfunction, hepatic and renal fibrosis, and myocardial remodelling." (PMID 33313931, 2021). "Confirming our dose range experiments, X203 reduced AKI-induced loss of kidney mass, limited renal fibrosis, and improved renal function while lowering inflammatory (Tnfα, Il6, Ccl2, Ccl5, Il1β), fibrosis (Col1a1, Col1a2, Col3a1, Fn1, Acta2) and tubular damage (Kim1, Ngal) markers." (PMID 36470928, 2022). "Hematopoietic TET2 or DNMT3A disruption promotes both cardiac and renal fibrosis in hypertensive cardiac remodeling mice model via elevated expression of inflammatory cytokines such as IL-6 and C-C motif chemokine 5 (CCL5)." (PMID 37928907, 2023). "TSN reduced renal fibrosis and improved pathological damage in the kidney in vivo through the regulation of GJA1, CTGF, MMP7, and CCL5, which are genes associated with ECM deposition." (PMID 34539795, 2021). "Furthermore, it was verified that TSN could regulate the levels of GJA1, CTGF, MMP7, and CCL5 and alleviate renal fibrosis in DN." (PMID 34539795, 2021). "The result is the increased expression of genes C-C Motif Chemokine Ligand 2 (CCL2) and C-C Motif Chemokine Ligand 5 (CCL5) and further renal fibrosis." (PMID 39125360, 2024). "A study reported that BMMSCs can decrease levels of tubular CCL-2, CCL-5, TNF-α, α-SMA, fibronectin (FN), and collagen IV and finally reduce tubular EMT and renal fibrosis in albumin-overloaded mice." (PMID 36268508, 2022). "As reported in recent literature, CCL-5 and IL-4 were modulated by NGAL produced from macrophages and were proved to play a critical role in renal fibrosis." (PMID 35585990, 2022). "Also, the levels of damage markers in renal fibrosis, including ED-1 α-SMA, IL-6, IL-1β, TNF-α, TGF-β, NF-κB mRNA, CCL-2, CCL-5, collagen I, FN, collagen IV, and PCNA are decreased." (PMID 36268508, 2022). "In biopsy specimens of patients with IgAN, CCL2, and CCL5, also known as regulated upon activation normal T-cell expressed and secreted (RANTES), as well as CCR5 were up-regulated and could play a role in renal fibrosis." (PMID 33670423, 2021).
uveitis (11 papers, 2007 to 2024). An inflammatory process affecting a part of or the entire uvea. "In contrast, uveitis in the BD patient had few of these effector CD4+ T cells but was characterised by clonally expanded effector CD8+ T cells expressing CCL5, GZMA, GZMB and PRF1." (PMID 37720629, 2023).